NES (nestin)
Diseases named in the same sentence as NES in open-access papers (continued):
Sharing a sentence is not in itself a finding about the gene and the disease.
tumor (continued). "In this research, RNA sequencing showed that LINC00162 is dramatically increased in patient‐derived tumour cell lines (PATC) compared with the human pancreatic nestin‐positive epithelial (HPNE) cells." (PMID 32364285, 2020). "While other biomarkers, such as CD44 and Nestin, were correlated with tumor staging, tumor size and lymph node metastasis." (PMID 31907037, 2020). "In the present study, only 12 out of 30 (40%) OSCC cases showed nestin positivity in the cytoplasm of the tumor cells." (PMID 31675305, 2019). "Based on these observations, it becomes strongly evident that nestin can be considered as a reliable marker of tumor angiogenesis." (PMID 31675305, 2019). "Nestin expression is correlated with tumor size, lymph node metastasis, and poor survival in NSCLC patients." (PMID 31126068, 2019). "To identify diffusely infiltrating tumor cells, we immunostained specimens used antibody of nestin and measured tumor area." (PMID 31296906, 2019). "Studies on nestin expression in carcinoma samples are inconclusive and contradictory, with a highly variable expression of nestin-positive tumor cells among various human cancers." (PMID 31675305, 2019). "Univariate analysis indicated that the ratio phosphorylated JNK/nestin in the tissue at a distance <1 cm from the tumor margin influenced the patients’ survival, having a prognostic implication." (PMID 30987226, 2019). "IF protein expression often becomes altered under inflamed tissue settings relative to homeostatic controls; such is the case for keratins in tumor-derived epithelia, as well as for vimentin and nestin in immune cell populations." (PMID 31126068, 2019). "For nestin, the general consensus is that it promotes cancer, as multiple studies showed that depleting nestin expression resulted in decreased xenograft tumor formation in vivo." (PMID 31126068, 2019). "Patient tumor tissue samples demonstrated a partial, cellular colocalization of integrin α10β1 and Nestin (1‒10% of the integrin α10β1 cells), while fewer of the integrin α10-expressing cells also expressed Sox2." (PMID 31027305, 2019). "Even though nestin-positive tumor cells were observed in various invasion patterns of OSCC, no statistical significance was observed." (PMID 31675305, 2019). "After establishing a stable overexpression system of mimic miR-330-5p through the lentiviral transfection of G15 cells, we performed a tumor sphere formation assay and measured the expression of stemness markers (Nestin, CD133, SOX9, and SOX2)." (PMID 31511040, 2019). "End-stage tumours were all confirmed by expression of human-specific nestin, which revealed a highly invasive growth pattern reminiscent of the parental patient GBM in situ." (PMID 31319548, 2019). "Data from this analysis suggest that GBM tumor cells are capable of migrating through the membrane pores, but that brain endothelial cells not only enhance this effect, but also increase nestin levels in the migrated cells." (PMID 31227783, 2019). "For instance, U87MG and LN18 GBM cells cocultured with clinical M2 GAMs showed increased colony-forming and tumor-sphere-generating abilities in association with increased stemness markers Sox2, STAT3, Wnt, and Nestin in the GBM cells." (PMID 31269723, 2019). "Accurate estimation of microvascular density (MVD) using nestin in tumors has revealed a strong relationship between tumor vessels and clinical outcome." (PMID 31675305, 2019). "For example, Nestin-positive progenitor cells in the cerebellum exhibit more efficient tumor cell transformation and severe genomic instability." (PMID 31695040, 2019). "Nestin cooperates with the Shh pathway to drive tumor growth and Nestin suppression inhibits cell proliferation and promotes differentiation in MB." (PMID 31297057, 2019). "The transferrin and anti-nestin antibody carrying system was shown to have a favorable pharmacokinetic profile and was effective in the reduction of the tumor volume in comparison to the treatment with TMZ." (PMID 30791358, 2019).
tumor (continued). "Both freshly dissociated tumor cells and cells collected from microfluidic chips showed higher expression of nestin." (PMID 30337660, 2018). "P5 regrowing tumor revealed almost complete loss of GFAP, diffuse nestin staining, and de novo focal EMA reactivity in a dot-like pattern, compared to the primary one." (PMID 29805974, 2018). "Here, we used transcriptomic and protein profiling of five tumour types to determine if EC nestin expression is modified in malignant tissue, and to determine its value as a prognostic marker for survival." (PMID 30279450, 2018). "In the present study, previously thought to reside exclusively in the cytoplasm, Nestin can also be found in the nucleus and participate in protecting tumor cells against cellular senescence." (PMID 30190500, 2018). "The present double immunostaining study showed that CD44 and Nestin were colocalized at the cell membrane of the tumor cells in the tumor periphery, demonstrating existence of stem cells expressing CD44 in the invasion area." (PMID 30210550, 2018). "Heterogeneous expression of nestin has been previously highlighted suggestive of the tumor heterogeneity." (PMID 30349420, 2018). "This stage shows the highest density of nestin+ cells (nestin-LI of 16.67 ± 1.36) and a clear pattern of distribution in the border area of the tumour." (PMID 30140373, 2018). "Immunostaining at d52 revealed that most of the orthotopic tumor expressed the stem cell marker nestin, indicating its stem cell-driven character." (PMID 30242200, 2018). "The immunofluorescence staining of the GBM tumors with tumor specific markers evaluated the impact of the brain microchip’s microenvironment on the expression of Nestin, VEGFR2 and GFAP." (PMID 30337660, 2018). "Here, the authors show that nuclear Nestin prevents senescence in tumor cells by stabilising lamin A/C from proteasomal degradation to maintain nuclear integrity." (PMID 30190500, 2018). "In stage III, nestin+, CD133+ and nestin/CD133+ cells are found aggregated into SAs distributed thorough the neoplasia, in perinecrotic areas or close to aberrant microvessels." (PMID 30140373, 2018). "We further show that Nestin stabilizes lamin A/C for maintaining nuclear integrity and protecting tumor cells from senescence." (PMID 30190500, 2018). "The identities of both primarily cultured p-GBM tumor cells were confirmed by analyzing the expression of specific markers (sox2, nestin for GBM neural stem cells; GFAP, NeuN for differentiated GBM tumor cells)." (PMID 29527330, 2018). "We finally identified that nestin-staining was suitable to discriminate primary cultured tumor cells from patient-derived fibroblasts." (PMID 30123089, 2018). "FK506 is capable of reversing this mechanism, as the treatment of FK506 in combination with Vc showed, reducing tumor volume as well as reducing GFAP, nestin, and Ki67 levels, which are associated with GBM aggressiveness." (PMID 30208561, 2018). "For instance, we identified Nestin (NEST)—a protein involved in the regulation of G2/M transition—to be up-regulated in the tumor compared with the peritumoral tissue." (PMID 29363612, 2018). "After tumour proliferation arrest, the nestin+ cells re-entered the cell cycle and produced highly proliferative cells that contributed to tumour relapse." (PMID 29991569, 2018). "Together, these results show that Nestin appears to protect tumor cells from senescence by stabilizing lamin A/C." (PMID 30190500, 2018). "A recent meta-analysis of the studies reported in literature in these last years provided evidence that only CD133 and nestin showed an increased expression with increased tumor malignancy and had in the majority of studies a prognostic significance." (PMID 30279357, 2018). "In the present study, we revealed that Nestin occurred in the natural context of tumor nucleus in culture and tissues in situ by microscopy, as well as subcellular fractionation." (PMID 30190500, 2018).
tumor (continued). "CD133(+) subpopulation formed sarcospheres, which played a role in initiating and sustaining tumor growth as well as stemness genes expression of Nestin, Sox2, OCT3/4, and Nanog." (PMID 30349420, 2018). "The available evidence suggests that the nuclear Nestin regulates the homeostasis of nuclear lamina and involves in the tumor cellular senescence." (PMID 30190500, 2018). "In turn, the expression of Glial Fibrillary Acidic Protein (GFAP) as a marker of differentiated astroglial cells, and nestin as a marker of neuronal stem cells, was evaluated in the tumor samples of treated animals." (PMID 30208561, 2018). "Although several studies reveal the involvement of Nestin in tumor cell migration, invasion, and metastasis, the roles and molecular mechanisms of Nestin expression in cancers remain elusive." (PMID 30190500, 2018). "Nestin and CD133 have been associated with GSLCs located in perivascular niches of tumour microvessels." (PMID 30140373, 2018). "Knockdown of Nestin in PDAC cells led to a reduced tumor incidence and volume as well as reduced formation of metastases in a murine PDAC model." (PMID 30167093, 2018). "The findings establish a role for nuclear Nestin in tumor senescence, which involves its nucleus-localized form and interaction with lamin A/C." (PMID 30190500, 2018). "The graft presented features of a tumor largely composed of Nestin-positive undifferentiated neural cells in the UbC-iC9-253G1 hiPSC-NS/PCs grafted group, as in the EF-iC9-253G1 hiPSC-NS/PCs grafted group." (PMID 28262544, 2017). "In surgical samples of this study, nestin expression in tumor cells was observed in 3 of 3 (100%) PCs." (PMID 28358810, 2017). "Overall, these neoplasms appear to be generally composed of a ‘core’ expressing few biomarkers surrounded by a region of nestin- and GFAP-positive cells with small numbers of neurons interspersed throughout the two." (PMID 28493990, 2017). "Nestin expression was also observed in the cytoplasm of vascular endothelial cells and fibroblasts in tumor stroma in each case." (PMID 28358810, 2017). "In this autochthonous model, tumors are initiated via in vivo viral transduction of endogenous Nestin-expressing progenitors of the neonatal mouse brainstem, and tumor symptoms develop within 3–5 weeks of virus injection." (PMID 28052119, 2017). "VDAC1-based peptide tumor treatment eliminated GSCs, as reflected in the marked decrease in the expression levels of all tested stem cell markers, namely Sox2, Nestin, CD133, Klf4, S100B and NGFR." (PMID 28412744, 2017). "TfR1 was expressed by CD133-positive tumor cells and to a limited degree by nestin-positive tumor cells." (PMID 28837569, 2017). "We further stained the NTN1FH tumor sections for nestin and HA to localize NTN1 positive cells in the tumors." (PMID 28069038, 2017). "The GFAP/Nestin double positive phenotype was also found, at a reasonable frequency (1.2 ± 0.3%; n = 14 tumor samples), in the original tumor tissue." (PMID 29163787, 2017). "Five patients (14%) showed discordant Nestin status between the primary tumour and the corresponding metastasis." (PMID 28439082, 2017). "Although the cells that give rise to tumors in Tsc1-null mice are expected to express nestin, only rare tumor cells preserved this expression, likely because of inactivity of the endogenous (mouse) nestin promoter upon differentiation of tumor cells." (PMID 29184052, 2017). "We noticed that tumor cells grew into 3 dimensional spheres and almost all of the cells were nestin positive." (PMID 29100360, 2017).
tumor (continued). "We observed that in the NTN1 expressing U87MG xenografts tumors the boundary of the tumor and the normal brain tissue was positive for stemness indicating marker nestin." (PMID 28069038, 2017). "Their investigation found that WNT signaling-activated TCF7-SOX2-NESTIN cascade was responsible for the tumor formation." (PMID 28157212, 2017). "Staining for human nestin (hNestin) showed a very infiltrative tumor growth with onset in the injected cerebral hemisphere." (PMID 28148893, 2017). "Reducing APLNR levels in GSC#9 markedly decreased tumour development, NESTIN overall staining and only mildly affect tumour vascularization." (PMID 29053791, 2017). "The data showed that the percentage of Nestin-positive tumor in the vehicle-treated control mice was 28.90 ± 1.76%, compared to 56.07 ± 1.87% of cell in tumors exposed to bevacizumab treatment (vs Control: p < 0.001)." (PMID 29228586, 2017). "Nestin positive tumours more often showed blood vessel invasion (OR 2.6, Series II), but not lymphatic vessel invasion." (PMID 28439082, 2017). "Tumor initiation was studied in nestin-positive neural and glial progenitor cells located in the frontal, periventricular region—the cells implicated in the formation of and a common location for human GBM." (PMID 28358926, 2017). "As the intermediate filament protein nestin is expressed in a very high fraction of tumour cells, we used it as a tumour marker." (PMID 27283525, 2016). "The nestin expression in the core spheroid and the invasive cells in vitro was very pronounced for T78, appearing as if most of the tumor cells expressed nestin." (PMID 27454178, 2016). "Stem cells markers CD44 and Nestin were decreased in tumour samples from mice treated with vincristine combined with MRS1220, compared to the vehicle group." (PMID 27634913, 2016). "The cell–cell intercommunication as key factor for tumor progression has became a research priority, and increasing evidence of leukemic blasts supported by Nestin+ MSC indicates their ability for long-term maintenance at the disease onset." (PMID 28111575, 2016). "Notch activation led to upregulating the expression of GSC markers such as CD133, Nestin, Bmi1, and Olig2, maintaining GSCs pool and phenotype, and growth of tumor neurospheres and xenografts." (PMID 26977157, 2016). "Brain tissue sections from HF2303 and MGG8 implanted mice were co-immunolabeled with antibodies against human-specific Nestin to label the tumor, and CD31 to label brain microvasculature." (PMID 27863376, 2016). "The images of immunofluorescence staining demonstrated that the cancer stem-like cell markers CD133 (green) and nestin (red) were expressed on the membranes of tumor spheres." (PMID 27801803, 2016). "The mean intensity of fluorescence (Total MMPs/Tumor Size), Vimentin and β-catenin (especially in nuclear) decreased, while E-cadherin increased significantly in the Si-Nestin treated group as compared to the Si-Control group." (PMID 27412382, 2016). "Tumour-derived cultures are usually similar to neural stem cell cultures in that NES-, GFAP-, OLIG2- and TUBB3-positive cells are all present." (PMID 27991551, 2016). "Immunostaining for nestin revealed that the morphology of tumour cells changed in the treated animals compared to controls." (PMID 27283525, 2016). "Nestin expression was significantly higher in tumor tissues as compared to adjacent non-tumor tissue." (PMID 27412382, 2016). "IHC revealed a high percentage of tumor cells that expressed nestin and EpCAM in all of the tumor samples." (PMID 27414409, 2016). "c-Myc also enhances the tumor forming capacity of nestin-expressing progenitor cells in medulloblastoma." (PMID 27148537, 2016). "A very recent study performing high-throughput analysis of NMIBC revealed a Class 2 tumor that associates with progression, these Class 2 tumors enriched for cancer stem cell markers such as ALDH1A1, ALDH1A2, PROM1, NES and THY1." (PMID 27655672, 2016).
tumor (continued). "When tumor tissues become hypoxic or hindered by the lack of nutrition, proangiogenic factors, such as vascular endothelial growth factor (VEGF) and nestin, predominate and result in angiogenesis and tumor progression." (PMID 26170886, 2015). "They engineered an associated mutation in Janus kinase 2 (JAK2) in HSCs and detected damage of the bone marrow niche through Nestin+ MSCs reduction, which further drive HSCs into neoplasia." (PMID 26236348, 2015). "Recent studies showed that an effective marker for in vivo tumor angiogenesis is nestin, an intermediate filamentous protein that is considered to be a marker of endothelial proliferation." (PMID 25913374, 2015). "In this perivascular region the GBM cells have a much stronger expression of nestin than in other parts of the tumor specimen." (PMID 26292663, 2015). "Nestin protein expression was immunohistochemically detected in 13% of the tumor cells of 6 epithelioid mesotheliomas." (PMID 26421614, 2015). "Co-staining of tumor cells (human-specific nestin) and leukocytes (rat-specific leukocyte common antigen or CD45) revealed the pattern of host cell infiltration in the xenografts." (PMID 26291724, 2015). "The center of the implant was populated by clusters of tumor cells which strongly expressed nestin, a neuronal stem cell marker and, to a lesser degree, GFAP, an astrocyte differentiation marker." (PMID 25919028, 2015). "Nestin was expressed at high levels by virtually all tumor cells while ~30–40% of the cells expressed GFAP and βIII tubulin was weakly present in ~5–8% of the cells." (PMID 25919028, 2015). "Another factor contributing to effective identification of nestin-positive endothelial cells was the scarce markings of other cells (e.g. tumor parenchymal cells)." (PMID 26018884, 2015). "The staining pattern for Nestin was similar to that observed in the GEM, with expression in invasive cells and intense staining around the necrotic tumor area (Nestin and Nestin/I)." (PMID 25431423, 2015). "Intriguingly, expression of EGFRvIII positively correlates with the expression of stem/progenitor markers, including Nestin, Sox2, and CD133, and is associated with an enhanced ability to self-renew and initiate tumor." (PMID 25992628, 2015). "Nestin was also reported to be expressed in tumor development including neurocytomas, pancreatic tumors, osteosarcomas, and gastrointestinal tumors and normally used as an angiogenesis marker in these tumors." (PMID 26236348, 2015). "The Classical glioma subtype has an astrocytic signature; EGFR amplification is commonly observed in this tumor type as well as high expression of Nestin (a neural precursor and stem cell marker), and Notch and Sonic hedgehog signaling pathways." (PMID 25955030, 2015). "NESTIN (along with CD133) has also been regarded as a CSC marker in disseminated tumor cells of metastatic melanoma patients." (PMID 26649310, 2015). "The distribution of the neural progenitor markers Nestin and Sox-2 aligned with other models in that Nestin expression was cytoplasmic and mainly in the tumor periphery, whereas Sox-2 was expressed in the nucleus by the majority of proliferative cells." (PMID 25431423, 2015). "Recent studies have reported that tumor cells with high expression of nestin show rapid proliferation." (PMID 24966803, 2014). "Previous studies have reported nestin expression in proliferating endothelial cells in the developing pancreas, during wound healing and tumor vascularisation." (PMID 25139503, 2014). "We observed nestin-positive tumor cells in the majority of NSCLC samples and significant association of nestin expression with the subset of NSCLC patients displaying poor outcomes and high levels of proliferative markers." (PMID 24498263, 2014). "Nestin expression in tumor cells was immunohistochemically studied in 93 patients with UCB who underwent radical cystectomy with pelvic lymphadenectomy." (PMID 24785714, 2014).